IL4 (interleukin 4)
Diseases named in the same sentence as IL4 in open-access papers (continued):
Sharing a sentence is not in itself a finding about the gene and the disease.
cancer (continued). "High expression of IL-4 in patients with cancer is strongly correlated with poor survival." (PMID 27895317, 2016). "To see whether IL-4R expression could be related to an anti-cancer effect of IL-4, we investigated the IL-4R expression pattern in several cancer cell lines." (PMID 26993600, 2016). "Recently, many studies have tested the association between different forms of cancer and functional variants of genes responsible for the inflammatory process, such as interleukin 1A (IL1A), interleukin 4 (IL4), nuclear factor kappa B1 (NFKB1) and protease-activated receptor 1 (PAR1)." (PMID 26879815, 2016). "In addition, sphere formation ability and expression of the cancer stem-like cell proteins, Sox2, and Oct4 were upregulated by recombinant IL-4 and downregulated by anti-IL-4 antibody in A498 cells, similar to the phenomena exhibited by MDA-MB-231 cells." (PMID 27895317, 2016). "Indeed, constitutive IL-4 expressing cancers have demonstrated reduced growth in vivo due to the induction of a robust antitumor immune response." (PMID 26498838, 2015). "Also, IL4 has been discovered to exert anti-angiogenic properties in several cancer models with high VEGF expression levels." (PMID 26437765, 2015). "Contradictory findings have been reported that suggest IL-4 could either enhance or inhibit cancer cell proliferation in vitro depending on the cancer cell type." (PMID 27563494, 2015). "It will also be important to determine how cancer cell derived IL4 influences other immune cell types including other myeloid cells as well as lymphoid cells, and their interactions with one another in the context of innate and adaptive immunity, as well as immune suppression." (PMID 27563494, 2015). "Previous reports have suggested that IL-4 could either promote or inhibit cancer cell proliferation in vitro by exerting effects through binding to IL-4R expressed on cancer cells." (PMID 27563494, 2015). "This M2-like macrophage activation by cancer cell derived IL-4 was also apparent in vivo when these IL4-AC2M2 cells were used to generate orthotopic tumors in mice, as shown by increased arginase I expression in tumors, seen by both IHC and immunoblotting analysis." (PMID 27563494, 2015). "IL-4 is also known to trigger the cancer proliferation mechanism." (PMID 26500775, 2015). "Consequently, several biomarkers have been reported to reflect the link between inflammation and cancer, such as interferon-gamma/interleukin-4 ratio and inflammation-based prognostic score (Glasgow prognostic score) based on CRP and albumin levels." (PMID 25885254, 2015). "In summary, immunological control of cancer cells with high COX-2 expression by antigen-specific T cells may be less effective because of increased local release of IL4 and IDO and blunted interferon-gamma secretion by antigen-activated cytotoxic T cells." (PMID 25501829, 2014). "We found an association between IL-4 intron 3 VNTR polymorphism and cancer risk." (PMID 25484626, 2014). "In addition, several important studies about the association of IL-4 intron 3 VNTR polymorphism and cancer risk have been published recently." (PMID 25484626, 2014). "Thus, it is very clear that though [AP1-V12]6 has minimal effect on cell growth, it can inhibit IL-4 mediated cancer cells proliferation probably by binding the IL-4 receptor expressed on cancer cells." (PMID 24339977, 2013). "In cancer, considered to be a Th2-dominant disease with excess of IL-4, IL-5, IL-10, and TGF-β production, a therapeutically driven shift back toward the Th1 profile is of interest, as it might correlate with immune and perhaps clinical recovery." (PMID 23730621, 2013). "This property, candidates IL-4 as a new agent for gene cancer therapy." (PMID 23493491, 2011). "Although the study was designed to study inflammatory arthritis, knowledge gained about IL-4 could be used for the treatment of cancer in the future." (PMID 20445741, 2010).
cancer (continued). "Second, cancer cell-derived IL-4 may exert paracrine functions on surrounding infiltrating immune cells, inhibiting immune responses." (PMID 15714203, 2005). "In the present study, we have compared the secretion of two important immunomodulatory cytokines, IFN-gamma and IL-4 by individual, immunophenotyped NK cells freshly isolated from either malignant tumour biopsies, or peripheral blood samples from patients with ductal invasive breast cancer." (PMID 1911184, 1991). "Studies have shown that interleukin-10, along with other interleukins such as IL-1 and IL-4, can activate pathways like NF-κB, contributing to cancer radioresistance; therefore, strategies to inhibit IL-10 or its signalling pathways could enhance the efficacy of radiation therapy." (PMID 39682192, 2024). "Thus, IL-4 blockade may become a standard regimen for anti-cancer therapy to prevent the development of MDCSs." (PMID 38474078, 2024). "After exposure to multiple inflammatory microenvironmental factors, molecules such as IL-4, IL-6, IL-8, IL-17α, IL-22, IL-23, IL-33, and interferon-γ, induce complex genetic/molecular changes in precancerous stem cells (pCSC) to gradually form cancer stem cells (CSCs)." (PMID 39073546, 2024). "Surprisingly, we also found that some immune-associated pathways upregulated in low-risk score groups in HNSCC, such as response to interleukin 4 and B cell receptor signaling pathway, implying our ERS-associated signature might be associated with immune surveillance against cancer cells." (PMID 37087456, 2023). "However, it is found that the classical type 2 immune cytokines IL-4, IL-5, IL-9, and IL-13 may have conflicting roles in cancer." (PMID 37455828, 2023). "Therefore, the cooperated actions by these cytokines (IFN/IL-6/IL-4) on TAMs might represent a common theme in some human cancers." (PMID 36726024, 2023). "Hence, studies show that IL-6 may help sustain cancer stem cell populations and increase EMT, whereas IL-4, CCL-2 and exosomal miRNA from cancer cells cause M2 polarization of TAMs." (PMID 37173970, 2023). "Therefore, potential strategies for cancer treatment may involve injecting high levels of IL-4 or blocking existing IL-4-signalling in patients." (PMID 37455828, 2023). "Thus, not only the distinct expression levels of respective receptor chains, but also the ratio between IL-13Rα1 and IL-4Rα expression may be crucial for the effect of IL-4 and IL-13 on the cancer cell phenotype." (PMID 35409019, 2022). "However, there were IL-4, IL-17, and IL-1β decreases in the patients with cancer (p < 0.05)." (PMID 34518597, 2021). "Thus, we have identified that overexpression of VSTM2L induced resistance to CRT in cancer cells through downstream IL-4 signaling which could affect the progress of cell proliferation and apoptosis." (PMID 33506057, 2021). "Whether IL-4 plays a protective or cancer-promoting role in GIT carcinogenesis is controversial." (PMID 32512917, 2020). "IL-4 leads to the development of RA through the pathways of cytokine-cytokine receptor interaction, Th1 and Th2 cell differentiation, Th17 cell differentiation, T cell receptor signaling pathway, pathways in cancer, and hematopoietic cell lineage and shows the characteristics of female dominance." (PMID 33426089, 2020). "We focused our stapler engineering efforts on the interleukin-4 (IL-4) cytokine, a member of the family of common γ-chain (γc) cytokines, which are critical for lymphocyte homeostasis and have been used to treat diseases such as cancer, chronic infection, and autoimmune disorders." (PMID 31387945, 2019). "Therefore, further studies are required to clarify the real function of IL‐4 in cancers." (PMID 30729744, 2019). "Furthermore, MSCs can differentiate into cancer-associated fibroblasts (CAFs) that produce high levels of IL-4, IL-10, TGF-β1 and vascular endothelial growth factor (VEGF) and regulate epithelial-mesenchymal transition (EMT) mechanism, thus they support cancer cell survival and metastasis." (PMID 28367424, 2017).
cancer (continued). "Besides mediating its biological functions, IL-4 could also promote the proliferation and survival of several cancer cells." (PMID 28927416, 2017). "To date, it remains unclear whether TMEM16A can be regulated by IL-4 and IL-13 in cancer cells." (PMID 28893247, 2017). "Thus, a continuous expression of IL-4 may provide an effective therapy for various diseases, including cancers and immunologic disorders." (PMID 27121311, 2016). "Furthermore, according to Okada and Kuwashima, the sustained expression of IL-4 may provide effective means for therapy of a variety of diseases, including cancer." (PMID 26989335, 2016). "Allelic variants of the interleukin 1A (IL1A), interleukin 4 (IL4), nuclear factor kappa B1 (NFKB1) and protease-activated receptor 1 (PAR1) genes may influence not only the inflammatory response but also susceptibility to cancer development." (PMID 26879815, 2016). "Therefore, our studies with selected miRNA-340/429, which targeted IL-4, might be a potential approach for cancer treatment." (PMID 27895317, 2016). "Undoubtedly, therefore, involvement of certain interleukins including IL-6, IL-4, IL-17A and IL-32β in certain EMT pathways signifies their specific contribution to metastatic processes, thereby warranting further work into the development of diagnostic and immunotherapeutic tools in cancer." (PMID 25590298, 2015). "This suggests that IL-4 may be of general importance for cancers to gain therapy resistance." (PMID 24728412, 2014). "Various studies have identified IL-4 or IL-6, produced by enterocytes and lamina propria myeloid cells, to a play critical role in both the survival and proliferation of pre-malignant intestinal epithelial cells as well as resistance of cancer stem cells to therapeutic treatments." (PMID 24970802, 2014). "IL-4 and IL-4R may also be involved in modulating Th1 and Th2 T-cell responses to cancer." (PMID 25208941, 2014). "A chimeric protein composed of human IL-4 and a full-length PE molecule with mutation in the cell binding domain of PE, hIL4-PE4E, was cytotoxic (with 50% inhibition of protein synthesis [IC50] occurring in the 12–120-pM range) to a wide range of human cancer cell lines." (PMID 22400035, 2012). "There are many cytokines and chemokines that can facilitate cell fusion; however, the most relevant to cancer are platelet-derived growth factor (PDGF), tumor necrosis factor alpha (TNF-α), epidermal growth factor (EGF), and interleukin-4 (IL-4)." (PMID 40723152, 2025). "Key molecules for cancer progression were inhibited (IL6, IL4, CXCL8, CXCR4, CXCL12; ICAM1, CD44 and BCL2), and pro-apoptotic BAD was activated." (PMID 41595551, 2025). "Despite its relatively low expression in tumors, IL-4 signaling can have profound effects on TME programming, as even a small fraction of IL-4-producing cancer cells can drive significant immune suppression." (PMID 40330466, 2025). "Cytokines produced by Th2 cells, including IL-10, IL-4, and TGF-β, can promote the dissemination and metastasis of cancer cells in various cancers." (PMID 40356980, 2025). "Quantification of the markers within specific cell type compartments revealed higher IL-4 mRNA expression in intratumor myeloid cells than in cancer cells, as well as lower TAP2 protein levels in cases with high myeloid cell IL-4 mRNA expression." (PMID 40091029, 2025). "This condition results in an expansion of splenic Treg and Th2 cell populations, elevated levels of IL-4 and IL-10, and an increase in local hypothermic Treg cells along with higher TGF-β1 concentrations in the cancer, thereby facilitating lung metastasis." (PMID 40881864, 2025). "The dominance of the Th2 subset is also evident by the enriched levels of type-2 cytokines, including IL4 and IL10, in the coculture of cancer and immune cells." (PMID 39544930, 2024).
cancer (continued). "Soluble factors such as cytokines (e.g., VEGF, IL-4, and IL-10), chemokines (CCL2, CCL5, CCL7, and CCL22), and enzymes like COX-2, IDO, and MMPs have a direct effect on the suppression of anti-cancer immune responses." (PMID 39409110, 2024). "Some studies and publications have reported a relationship between dysregulation of expression of some cytokines, including IL-1, IL-2, IL-4, IL-6, LPC2, TNF-α, etc., and incidence of cancer, cancer invasivity, and metastases." (PMID 38541074, 2024). "Loss of Lect2 fosters the accumulation/activation of M-MDSC, leading to the presence of M2-like TAMs and pro-tumorigenic cytokines (IL-4, IL-6, IL-10, and TGF-β) that can impair the activity of T cells in the fight against cancer." (PMID 38177412, 2024). "Interleukin-4 (IL4) is a Th2 cytokine that can signal through two different receptors, one of which—the type II receptor—is overexpressed by various cancer cells." (PMID 38731867, 2024). "Moreover, some immune-associated pathways that upregulated in low-risk score groups in HNSCC, such as response to interleukin 4 and B cell receptor signaling pathway, imply our ERS-associated signature might be associated with immune surveillance against cancer cells." (PMID 37087456, 2023). "Compared to drug-sensitive cancer cells, MDR cancer cells have augmented autocrine formation of growth factors such as interleukin (IL)-1, IL-6, IL-4, and IL-8." (PMID 37062547, 2023). "Most IL-4-induced innate CD8 T cells express CXCR3; such cells enhance immunity against bacterial infection and cancer." (PMID 38037190, 2023). "In cancer settings, CD4+CD8+ cells were shown to produce IL-4 themselves, thus probably promoting the induction of IL-4-related programs." (PMID 35222424, 2022). "IL-4 is a pleiotropic cytokine that has two important roles: it promotes the proliferation of immunoglobulins and their class switching, and it inhibits the growth of cancer cells in vitro, which may be due to its ability to increase the host antitumor response." (PMID 35974992, 2022). "Recently, IL4 and IL13 have been considered not only target for inflammatory diseases but also the therapeutic target of cancer." (PMID 35207737, 2022). "Concurrently, S100A8 significantly decreased protein levels of IL-4 (381.0 ± 66.6 pg/mL to 194.3 ± 34.2 pg/mL, p < 0.05) and IFN-γ (121.5 ± 16.5 pg/mL to 22.1 ± 5.5 pg/mL, p < 0.0001) in BALF from mice with LLC cancers to basal levels." (PMID 35655772, 2022). "Considering the close relationship of IL-4 with TAMs, there is little surprise that IL-4 was shown to induce the ability of TAM-derived cathepsin protease, leading to cancer progression, invasion, and angiogenesis." (PMID 33804263, 2021). "CD4+ T cell subsets, such as Th1, Th2, Th17, and regulatory T (Treg) cells, serve pivotal functions in cancer immunity, among which the Th2 subset of CD4+ T cells secretes IL-4, IL-5, and IL-13, and activates B cells to become antibody-secreting plasma cells." (PMID 35069553, 2021). "IL-4 and IL-13, produced by multiple components in the TME, mediate a wide range of functions in a variety of cancers through appropriate receptors." (PMID 33804263, 2021). "On the other hand, TH2 cytokines IL-10, IL-4 and TGF-β from TH2 cells can promote dissemination of cancer cells dissemination and metastasis in various cancers." (PMID 34012451, 2021). "In addition, IL-4-binding fusion protein APG598 and IL-4R antagonist APG201 (R121D/Y124D) improved the chemosensitivity of Hodgkin lymphoma cells, which indicates that the combination of classical chemotherapy with IL-4/IL-13 antagonists may improve the efficacy of the both in cancer treatments." (PMID 33804263, 2021). "The up‐regulation of IL‐4, IL‐5 and IL‐10 as seen in our MRMT‐1/Luc2‐bearing animals is in agreement with previous data and is indicative for cancer physiology modulation." (PMID 31724155, 2021).
cancer (continued). "Under these conditions, a sequential action of IL-4/IL-13 and IGF-I targeting on macrophages and cancer cells, respectively, culminates in cancer progression." (PMID 34769439, 2021). "When more SP is released, it can decrease the apoptosis subsequently by modulating the immune markers IL4, IL6, and IL10, resulting in unrestrained cell division, cell progression, and prominent cancer metastasis." (PMID 34692834, 2021). "IL-4-IL-4R signaling is involved in CD133+ cancer stem cell survival and proliferation in CRC, which are therapy-resistant cells due to the autocrine production of IL-4." (PMID 33233582, 2020). "For the purpose of correlation analysis we have retrieved data on systemic concentrations of IL-1β, IL-4, IL-6, IL-8, IL-12p70, FGF2, G-CSF, GM-CSF, MCP-1, MIP-1α, PDGF-BB, TNFα, and VEGF-A, available for 43 of our cancer patients." (PMID 33020452, 2020). "Taking into account a wide spectrum of cancer-promoting activities of MCP-1 or COX2, the downregulation of their expression induced by IL-4 seem to support anti-neoplastic character of the interleukin." (PMID 32512917, 2020). "Other molecules described to be expressed in neutrophils in the cancer niche are MMP-9, IL-4, and IL-10 (although very controversial)." (PMID 32117288, 2020). "IL4 and IL13 bind to their receptors specifically, and both cytokines can have effects on cancer cells expressing appropriate receptors." (PMID 31540495, 2019). "TAMs have also been found to significantly overexpress immunosuppressive cytokines IL-4, IL-10 and TGF-β in human and mouse cancers." (PMID 31629410, 2019). "Factors involved in EMT in cancer include TNF, IL-1, and IL-4, which in turn activate several transcription factors that promote EMT." (PMID 31337349, 2019). "On the front of cancer cells, both TMZ-R and TMZ-S cells showed a significant increase in the M2 cytokines mRNA level of IL-10, IL-4, IL-13 and CCL2 as compared to their parental counterparts." (PMID 31462285, 2019). "Fractalkine, GRO, IFNα2, IFNγ, IL-4, and MDC are also thought to play a role in the development of cancer cachexia." (PMID 30513792, 2018). "Our results show that IRF8 complexes boost the Th9 program and repress Il4 expression to modulate Th9 cell differentiation, thereby implicating IRF8 as a potential therapeutic target to affect Th9 responses in cancer therapy." (PMID 29233972, 2017). "We further included the 9 known cancer-signaling pathways from the NetPath database, namely, EGFR1, FSH, IL-1, IL-4, IL-5, Leptin, RANKL, TNF-alpha, and TSH." (PMID 29190299, 2017). "Th1 mediates cellular immunity, which is able to capture intracellular bacteria, viruses, and cancer, inducing the secretion of IFN-γ cytokines, a Th2 response to humoral immunity, and IL-4 secretion." (PMID 28819629, 2017). "As a result, we successfully established CD14-ML from monocytes obtained from the 2 cancer patients (cancer patient 1 and 2), and the CD14-ML were able to differentiate into CD14-ML-DC after stimulation with IL-4." (PMID 27050553, 2016). "Here, we demonstrated that IR-induced IL-4 enhances epithelial-mesenchymal transition (EMT), migratory potential, invasiveness, angiogenesis, stemness, and metastasis of cancer cells or xenograft model." (PMID 27895317, 2016). "Polysaccharides isolated from A. annua L. (Huang-Hua-Hao) increase CD4+ and CD8+ T cells and IFN-γ and IL-4 secretion in HCC bearing mice, and induce cancer cell apoptosis in HCC." (PMID 26828466, 2016). "IL-4-induced STAT6 signaling is active in a variety of cell types, including immune cells and cancer cells, and plays an important role in the regulation of gene expression." (PMID 25333330, 2015). "Cancer cells promote the production of IL-4 and down-regulate the level of IFN-γ in cancer-encountered T cells." (PMID 26020249, 2015).